INHBA (inhibin subunit beta A)
Diseases named in the same sentence as INHBA in open-access papers (continued):
Sharing a sentence is not in itself a finding about the gene and the disease.
tumor (continued). "INHBA and THBS2 from cancer-associated fibroblasts are packaged into extracellular vesicles and secreted into the tumor microenvironment to promote gastric cancer." (PMID 34064083, 2021). "We observed that the tumor growth was significantly suppressed in the INHBA silencing group, while INHBA overexpression accelerated tumorigenesis." (PMID 34346300, 2021). "For example, INHBA (inhibin βA), a subunit of a ligand of the transforming growth factor-β superfamily, has been reported to be a tumor suppressor in DLBC, but a promotor in BRCA." (PMID 33766047, 2021). "Negative correlation between MT1G and INHBA was also observed in PDAC clinical samples, in which MT1G was down-regulated while INHBA was up-regulated in tumor tissues compared with the adjacent counterparts." (PMID 33537082, 2021). "Results suggest that INHBA was overexpressed in CRC tumor samples, cell lines and culture medium compared with normal ones." (PMID 34476008, 2021). "Methylated Solute Carrier Family 30 Member 10 (SLC30A10), claudin 1 CLDN1, and Inhibin Subunit Beta A (INHBA) were evidenced by SureSelectXT Methyl-Seq as being able to differentiate between normal and tumor tissue." (PMID 34638449, 2021). "This mimics the situation in human NMSC, where INHBA is up to 50‐fold overexpressed in total tumor samples compared to normal skin and even more in the cancer cells themselves." (PMID 32150356, 2020). "It was also discovered that INHBA is involved in cell proliferation in patients with high expressions, and correlated with the tumor-node-metastasis (TNM) stage and venous invasion, making it an independent factor of prognosis after radical gastrectomy for GC." (PMID 32647495, 2020). "Most importantly, when SCC13 cells were co‐injected with Fb Act or EV, tumor formation was strongly accelerated upon DOX‐induced INHBA expression." (PMID 32150356, 2020). "Previous studies have confirmed INHBA expression is related tumor invasiveness and promoting metastasis but the specific pathogenesis is unclear." (PMID 31586103, 2019). "Our data also demonstrate that Activin A signaling induces Smad-depended IL13Rα2 expression and that knocking down INHBA levels delays primary tumor growth and suppresses formation of lung metastases in vivo." (PMID 30805303, 2019). "Through comprehensive in vivo and in vitro experiments, we confirmed that knockdown of INHBA in tumor cells reduced OC stromal fibroblast activation, which turned to inhibit tumor growth." (PMID 31827640, 2019). "It was also discovered that INHBA is involved in tumor–node–metastasis (TNM) stage and venous invasion." (PMID 31586103, 2019). "This expression pattern is similar to the one observed in human SCCs and consistent with the expression of INHBA in tumor cells of AK and SCC patients isolated by laser capture microdissection." (PMID 27932444, 2017). "CTGF and INHBA (a member of the transforming growth factor β (TGF-β) superfamily) are the ones elevated in both tumor epithelial and stroma." (PMID 26318291, 2015). "CLDN1, INHBA, and CXCL12 may serve as clinically relevant biomarkers in CRC, particularly as prognostic indicators linked to tumor progression, immune modulation, and metastatic potential." (PMID 40426863, 2025). "Notably, INHBA is a well-known tumor promoter under tumor-bearing conditions, and AQP8 is upregulated under inflammatory conditions, highlighting their potential roles in lung pathology." (PMID 40843897, 2025). "INHBA encodes TGF-β superfamily members, and its decreased expression could affect TGF-β signaling, which is known to be involved in tumor progression, angiogenesis, and immune evasion." (PMID 40898538, 2025). "Furthermore, we conducted subcutaneous syngeneic tumor transplantation experiments in C57BL/6 mice via mouse cell models with INHBA knockdown." (PMID 41449244, 2025). "INHBA: Inhibin Subunit Beta A—A growth factor involved in tumor progression." (PMID 40075643, 2025).
tumor (continued). "This shows that INHBA expression in NSCLC may facilitate tumor development and can determine prognostic outcomes." (PMID 41463203, 2025). "Furthermore, the present study found a strong correlation between the expression of target genes (IL10RB, INHBB, NEO1, PIK3R1, BCL2, ID4, and INHBA) and the infiltration of tumor-killing cells into the tumor immune microenvironment in HNC." (PMID 40647469, 2025). "Furthermore, we found that INHBA protein treatment up-regulated three tumor inhibitory genes, namely EGR2, ERG3, and NR0B1." (PMID 38658971, 2024). "Aberrant expression of INHBA may expedite GC development by modulating the components of the tumor immune microenvironment." (PMID 39543755, 2024). "Furthermore, bulk RNA sequence analysis using this mouse model identified the inhibin subunit beta A (INHBA) gene to be specifically upregulated in AMs in the tumor microenvironment." (PMID 38720352, 2024). "Our results indicate that the upregulation of INHBA is tumor-promoting." (PMID 38329386, 2024). "However, the ratio of INHBA(+) fibroblasts (number of INHBA(+) cells / number of fibroblasts) was significantly higher in metastatic and recurrent samples compared to primary tumor samples." (PMID 38360876, 2024). "Yet, uncertainty exists regarding whether tumor development in vivo is slowed down by INHBA knockdown." (PMID 38329386, 2024). "Additionally, our ISH analysis of tumor sections from syngeneic mouse models showed that INHBA is expressed in the host CAFs only if they are in proximity of cancer cells." (PMID 38360876, 2024). "Here, we identified INHBA(+) CAFs as key players in tumor promotion and immunosuppression." (PMID 38360876, 2024). "We found that INHBA is likely involved in accompanying a pro-tumor microenvironment." (PMID 38329386, 2024). "The abnormal expression of Th1/Th2 might, in some cases, stimulate the host immune system, which leads to a systemic anti-tumor immune response, thereby promoting the expression of INHBA." (PMID 36984496, 2023). "It was suggested that the overexpression of INHBA in CC tissues might have an important relationship with tumor immune response." (PMID 36984496, 2023). "INHBA is involved in various biological activities, especially tumor development." (PMID 37940978, 2023). "The expression level of INHBA was relatively high in tumor tissues." (PMID 35216189, 2022). "Moreover, the tumor tissues from the advanced stage represented a much higher level of INHBA than those for early stage." (PMID 35236827, 2022). "Collectively, previous and new results indicate that INHBA may have a tumor-promoting effect in a variety of cancers." (PMID 35216189, 2022). "In conclusion, an immune‐related gene prognostic model was constructed, patients with high‐risk scores have poorer survival status, M2‐phenotype tumour‐associated macrophages (TAMs) up‐regulate two immune‐related genes, MMP14 and INHBA, which were used to establish the prognostic model." (PMID 35150061, 2022). "The expression of GRAMD1C, NFKBIA, and ACSS2 was significantly higher in normal tissues than in tumour tissues (P < 0.001, P = 0.0096, and P < 0.001, respectively), which indicated that CD24 and INHBA were risk genes and that GRAMD1C, NFKBIA, and ACSS2 were protective genes." (PMID 35999846, 2022). "INHBA depletion reduces tumor growth and migration in vitro." (PMID 35216189, 2022). "Moreover, in GC patients, the overexpression of INHBA in tumor tissue is reported to be related to poor survival." (PMID 36139587, 2022). "In addition, our data displayed that INHBA is highly expressed in a variety of tumor tissues, which provides a basis for the application of metformin in the treatment of other tumors by down-regulating INHBA." (PMID 35236827, 2022). "Additionally, M2-related macrophages, including INHBA+ monocytes and C1QC+ tumor-associated macrophages, were significantly increased in ASPCs, followed by a reduction in juvenile macrophages in the tumor microenvironment (FCN+ monocytes)." (PMID 36052088, 2022).
tumor (continued). "Notably, the expression of INHBA was greater in PDAC tumor tissue in comparison to that in matched normal tissue." (PMID 35102236, 2022). "Moreover, the mRNA expression of MMP14 and INHBA was significantly up‐regulated compared with non‐tumour samples in the Oncomine Pei pancreas cohort." (PMID 35150061, 2022). "In addition, patient collectives suitable for receiving activin A-targeting treatment, perhaps those with poor response to immune checkpoint blockade (ICB) or high expression of INHBA in tumor microenvironment, should be clarified." (PMID 35774793, 2022). "Next, human INHBA expression of different tumor types from TCGA was further determined by TIMER2.0." (PMID 36304286, 2022). "In conclusion, through comprehensive bioinformatics analysis, we successfully identified three hub genes (CTHRC1, FNDC1, and INHBA) that are differentially expressed between tumor and normal tissues in both TCGA-STAD and GSE66229 datasets and highly correlated with GC." (PMID 34968391, 2021). "Together, our results and previous studies indicate that INHBA may function as a tumor-promoting factor in a variety of cancers." (PMID 34346300, 2021). "In 9 CRC datasets, INHBA was substantially overexpressed in tumor tissues (log2 FC > 2)." (PMID 34476008, 2021). "Moreover, the higher expression levels of INHBA were correlated with the tumor tissues of the more advanced T-stages." (PMID 34103052, 2021). "INHBA expressions in CRC patients' tumor and adjacent tissues were quantified by IHC." (PMID 34476008, 2021). "Furthermore, IHC staining showed that both Ki-67 (cell proliferation marker) and INHBA were upregulated in the tumor tissues with INHBA overexpression, and downregulated in the tumor tissues after INHBA silencing." (PMID 34346300, 2021). "The differential effect on cancer cell proliferation in vitro and in vivo suggests that the inhibitory effect of INHBA knockdown in tumor growth in vivo may involve, to some extent, interactions with the tumor microenvironment." (PMID 30805303, 2019). "Our observations suggested that inhibition of INHBA in tumor cells could be a potential therapeutic approach to inhibit tumor progression and improve survival rates." (PMID 31827640, 2019). "Additionally, our results shed light on the activation role of OC cell-derived INHBA in stromal fibroblasts, which was via the p-Smad2 pathway and promoted tumor xenograft growth." (PMID 31827640, 2019). "Thus, considering the obvious prognostic significance of INHBA in SOC and limitations of in vitro experiments, we evaluated the role of INHBA in tumorigenesis in vivo using an immunodeficient mouse subcutaneous tumor model." (PMID 31827640, 2019). "Based on our previous studies suggesting that inhibition of IL13Rα2 delays tumor growth and suppresses formation of lung metastases, we wanted to investigate whether depletion of INHBA has a similar effect on metastatic MIV cells." (PMID 30805303, 2019). "We found that upon INHBA knockdown, primary tumor growth was delayed compared to control cells." (PMID 30805303, 2019). "Although the mechanism behind this altered expression remains to be clarified, these results provide an indication that INHBA functions as a tumor suppressor in DLBCL and may therefore be a target for treatment." (PMID 29225711, 2017). "For both microRNAs, a significant and inverse correlation with INHBA levels was observed in the cell lines (rho = -0.75 and p = 0.033 for miR-143, rho = -0.62 and p = 0.042 for miR-145) and fresh tumor samples (rho = -0.72 and p = 0.01 for miR-143, rho = -0.70 and p = 0.02 for miR-145)." (PMID 26317418, 2015). "However, the complexity of the immune microenvironment suggests that INHBA could also exert essential roles in other immune cells, including B cells, T cells, and dendritic cells, which critically shape the anti-tumor immune response." (PMID 41449244, 2025).
tumor (continued). "Additionally, flow cytometry analysis of syngeneic tumor samples revealed that exogenous succinate partially reversed the decrease in F4/80+CD11b+CD206+ and F4/80+CD11b+CD163+ macrophages proportion caused by INHBA knockdown." (PMID 41449244, 2025). "Moreover, immunohistochemical staining revealed elevated expression of CD8, GZMB, and CD11c in tumor tissues upon INHBA knockdown, indicating that silencing INHBA may enhance CD8+ T cells and dendritic cells (DCs) infiltration within the TME." (PMID 41449244, 2025). "Similarly, tumor proliferation was suppressed in INHBA-conditional KO mice." (PMID 38720352, 2024). "Thus, INHBA may have additional indirect effects that promote tumor growth beyond those that we have observed in our cell line studies." (PMID 35248133, 2022). "The molecular mechanism and tumor-promoting function of INHBA remain unclear." (PMID 35935970, 2022). "Our scRNA-seq dataset further showed that NLRP3+ and INHBA+ macrophages also expressed several well-characterized immune-suppressive tolerogenic molecules, suggesting efferocytosis can activate a unique heterogeneous complex signature in tumor-infiltrating mononuclear phagocytes." (PMID 36439171, 2022). "Together, these analyses indicate that INHBA might act as a tumor promoter in BC cells." (PMID 34346300, 2021). "Besides, INHBA was found significantly correlated with immune infiltration, especially T cells, which implied that INHBA might involve tumor immune regulation." (PMID 34476008, 2021). "Moreover, in terms of M staging, the median values of CXCL1 expression were relatively higher in M0 staging than in M1 staging, and for the tumor stage, the median values of INHBA expression and riskScore were significantly elevated in stage III-IV than in stage I-II." (PMID 32788867, 2020). "Finally, we contrast the INHBA expression between various tumor and normal tissue." (PMID 31586103, 2019). "We performed scRNA-seq analysis on CLDN1, INHBA, and CXC12, regulated by both miRNAs and DNA methylation, in COAD tumor and normal colon tissue using GSE178341." (PMID 40426863, 2025). "VEGFC, FGF1, INHBA, FYN, and AGTR1 promote angiogenesis, lymphangiogenesis, EMT, invasion, and tumor cell survival – constituting pro-metastatic signaling." (PMID 41006647, 2025). "INHBA is often over-expressed in COAD tissues, correlating with increased tumor aggressiveness, higher metastatic potential, and poorer prognosis." (PMID 40426863, 2025). "We subsequently performed subcutaneous syngeneic tumor transplantation experiments in C57BL/6 mice via mouse cell models with INHBA knockdown and restored SLC25A10 expression, as well as models with INHBA overexpression and SLC25A10 knockdown." (PMID 41449244, 2025). "INHBA is crucial in promoting EMT, cell proliferation, and an immunosuppressive tumor environment, suggesting its potential as a therapeutic target for HPV-negative OPSCC." (PMID 38329386, 2024). "We next examined the expression of the markers identified previously that showed good correlation with tumour volume -ALOX15, IL-1β, CSFR1, CD14 and INHBA - to their expression at the single-cell level in the macrophage subclusters." (PMID 38480935, 2024). "We showed that the initiation of EMT by INHBA is mediated by the upregulation of SNAI2 and SNAI1, rendering tumor cells more migratory." (PMID 38329386, 2024). "Subsequently, MMA has also been confirmed in vivo to increase the expression of INHBA, Ki-67, p-Smad2, p-Smad3, and EMT markers, according to immunohistochemistry, immunofluorescence, and western blotting assays of subcutaneous tumor tissues." (PMID 38252148, 2024). "Among them, INHBA, HSP90AA1, and EIF2AK2 were significantly higher expressed in tumor samples than in normal samples." (PMID 39006030, 2024). "To evaluate the clinical significance of inhibin beta family genes (INHBA, INHBB, INHBC, and INHBE) in STAD, we investigated their interrelations and compared their expression levels between tumor and normal tissues." (PMID 39543755, 2024).
tumor (continued). "We demonstrated that the upregulation of INHBA initiated by FOXA2 promoted MITF-mediated EMT and tumor progression in response to sustained MMA stimulation." (PMID 38252148, 2024). "For example, TGFB3-SDC4 and INHBA-TGFBR3 were found between POSTN+ fibroblasts and tumor cells and CXCL5-BDKRB2 and CCL7-ACKR2 were found between SPP1+ macrophages and tumor cells." (PMID 38519500, 2024). "A strong positive correlation was detected between the expression of INHBA and EMT transcription factors SNAI1 (Rho = 0.62), SNAI2 (Rho = 0.82), and TWIST1 (Rho = 0.69) in the primary tumor." (PMID 38329386, 2024). "Inhibin subunit beta A (INHBA) and SRY-box transcription factor 9 (SOX9) are known to influence cell differentiation and have been reported to increase tumor aggressiveness in NSCLC through induction of epithelial-mesenchymal transition (EMT)." (PMID 38674080, 2024). "Inhibin β A (INHBA) is the most widely expressed biomarker of the transforming growth factor-β (TGF-β) family in tumor cells, and has predictive value for tumor development and prognosis." (PMID 36984496, 2023). "Moreover, postnatal deletion of INHBA/activin A could limit tumor growth in experimental models." (PMID 36650150, 2023). "In our present set of tissue samples, differences in DNA methylation levels resulting in differences in the mRNA expression levels of the SPHK1, INHBA, LTB and PDE3B genes were correlated with poorer tumor differentiation." (PMID 36348017, 2023). "Among tumor-related genes characterizing Clusters I and II, differences in the levels of DNA methylation and mRNA expression for the SPHK1, INHBA, LTB and PDE3B genes were correlated with poorer tumor differentiation." (PMID 36348017, 2023). "In our study, the expression of KLF9, MCM2, INHBA, and CGREF1 was significantly correlated with TNM clinical stage and tumor differentiation, excluding tumor location, age, and sex." (PMID 37370046, 2023). "Screening for circulating tumor DNA from peripheral blood is low invasive and provides fast results, and we suggest screening for HPVP HNSCC using a panel, including RBM24, INHBA, SYCP2, TAFL7, and ZFR2." (PMID 36142875, 2022). "Subcutaneous xenograft nude mouse models confirmed that the growth of tumours was weakened by knocking down the expression of MMP14 and INHBA." (PMID 35150061, 2022). "Among these five prognosis-related genes, we found that INHBA and CD24 were oncogenic genes, while GRAMD1C, NFKBIA and ACSS2 were tumour suppressor genes." (PMID 35999846, 2022). "Within the tumor, only 3 mononuclear phagocytes - CD16+ monocytes, NLRP3+ macrophages, and INHBA+ macrophages – had elevated levels of NLRP3 and IL1B expression." (PMID 36439171, 2022). "Inhibinβ A (INHBA) is a member of the TGF-β superfamily that has multiple biological functions, including the promotion of tumor progression." (PMID 35338119, 2022). "As tumor STF2 (CSPG4-high) and STF3 (FAP-high) represent distinct CAF populations, we then performed a coexpression correlation analysis between INHBA expression and the respective cluster markers." (PMID 34642171, 2022). "In our integrated analysis of human colon mucosa and tumor fibroblasts, PDPN was prominently expressing in CXCL14+INHBA+ fibroblasts." (PMID 36463319, 2022). "In normal tissues, RPL22L1, INHBA, and CAPZA1 were found to be significantly increased in CRC patients for whom experienced tumor lymphatic metastasis." (PMID 35909892, 2022). "INHBA was expressed by tumor-adjacent spindle-shaped cells and expression levels were positively correlated with those of ATP1A1 at the tumor-stromal interface." (PMID 35618735, 2022). "Via gene expression, overall survival (OS), disease free survival (DFS) of TCGA database, INHBA and SLCO4A1 were found overexpressed in tumor tissues and significantly OS-/DFS- differential." (PMID 34476008, 2021).